MTOR (mechanistic target of rapamycin kinase)
Diseases named in the same sentence as MTOR in open-access papers (continued):
Sharing a sentence is not in itself a finding about the gene and the disease.
cholangiocarcinoma (continued). "In cholangiocarcinoma, overexpression of EPHA2 enhanced AKT/mTOR signaling, thereby promoting the proliferation of CHO-CK cells in vitro and tumorigenicity in vivo." (PMID 33834064, 2021). "Following the addition of the PI3K agonist (740 y-p), the levels of p-Akt, mTOR and p-mTOR increased, and 740 y-p eliminated the inhibitory effect of Tan-IIA on Cholangiocarcinoma cells." (PMID 34588580, 2021). "In our study, the characteristic profile of the choline metabolites in the cholangiocarcinoma cells treated by gemcitabine plus rad001 was most likely a result of a potent and selective targeting against the PI3K/AKT/mTOR signaling pathway." (PMID 29666220, 2018). "However, in cholangiocarcinoma, the role of miR-199a-3p and its relationship with mTOR are unknown." (PMID 28422725, 2017). "After exposing the cholangiocarcinoma cell lines RMCCA1 and KKU100 to oxaliplatin, the levels of Akt and mTOR phosphorylation increased, as shown by western blot analysis." (PMID 19128511, 2009). "In individuals with cholangiocarcinoma who express DCLK1 at high levels, inhibitors of the PI3K/AKT/mTOR signaling pathway may be an effective therapeutic approach." (PMID 38980538, 2024). "Moreover, metformin also sensitizes cholangiocarcinoma cells to chemotherapeutic agents such as sorafenib, 5-fluorouracil, and arsenic trioxide by regulating the AMPK/mTOR/HIF-1α/MRP1 pathway and ERK." (PMID 36837499, 2023). "Similarly, FGFR promotes cholangiocarcinoma cell progression and resistance to gemcitabine through upregulation of AKT/mammalian target of rapamycin (mTOR) and STAT3 signaling." (PMID 37750089, 2023). "Similarly, YAP knockout in the TKKK cholangiocarcinoma cells did not affect the Akt/mTOR signaling pathway, while VP significantly upregulated p-Akt and p-mTOR in HuCCT1 and TKKK cells." (PMID 33178014, 2020). "CCK-8 assay showed that suppression of mTOR led to greater sensitivity to cisplatin in GBC-SD and RBE cell lines, but the sensitivity of cholangiocarcinoma cells with mTOR knockdown to cisplatin was not changed when treated with miR-199a-3p mimics or inhibitor (***P < 0.001)." (PMID 28422725, 2017). "ZEB1, serving as a transcription factor promoting the EMT process, is associated with the stem-like properties of cholangiocarcinoma (CCA) cells, which can be explained by the fact that FBXW7 dampens EMT and stemness of CCA cells via the mTOR/ZEB1 signaling pathway." (PMID 35515121, 2022).
PEComas (62 papers, 2011 to 2026). "Perivascular epithelioid cell tumors (PEComas) are rare mesenchymal neoplasms characterized by myomelanocytic differentiation and dichotomic molecular pathogenesis (mTOR-activating mutations versus TFE3 gene rearrangements)." (PMID 41790187, 2026). "Molecular alterations in uterine PEComas frequently involve dysregulation of the mTOR signaling pathway, most often due to inactivating mutations in the TSC1 or TSC2 genes." (PMID 41463261, 2025). "Malignant perivascular epithelioid cell tumors (PEComas) are rare tumors in which the PI3K/AKT/mTOR pathway is critical for pathogenesis and is often associated with mutations in the TSC1/TSC2 genes." (PMID 40989692, 2025). "Recent studies have highlighted the role of TSC1/TSC2 gene mutations and mTOR pathway activation in PEComas, which not only contribute to tumorigenesis but also provide potential therapeutic targets." (PMID 41246713, 2025). "mTOR inhibitors showed similar outcomes as chemotherapy, suggesting that these should be preferred whenever possible for patients with PEComas given the morbidity associated with chemotherapy." (PMID 37448552, 2023). "Kenerson confirmed that the high expression of mTOR activity markers and the low expression of Akt in PEcoma are associated with the destruction of TSC function." (PMID 35928867, 2022). "The activation of the mTOR pathway through the loss of the tuberous sclerosis complex 1 (TSC1)/TSC2 repressor complex seems to be a common pathogenic event in PEComas." (PMID 34542724, 2021). "Regarding molecular characteristics, PEComas are characterized by mutations leading to mTOR pathway activation, such as TSC1 or TSC2 bi-allelic inactivation, TFE3 gene fusion and FLCN truncating mutations." (PMID 34680376, 2021). "Recently it has been demonstrated that PEComas are generated by the proliferation of PECs with mutations leading to loss of TSC gene activity resulting in overexpression of the kinase mammalian target of rapamycin (mTOR)." (PMID 31171030, 2019). "In only perivascular epithelioid cell tumors (PEComas), which are known to be linked through activation of the mTOR pathway, a high rate of response to the mTOR inhibitor sirolimus was observed, and small case series and case reports have been reported." (PMID 29510588, 2018). "Longer-term therapeutic responses with significantly improved efficacy over chemotherapy can be achieved with mTOR inhibitors in malignant PEcoma, especially in patients with mutations in the TSC1/TSC2 genes that result in aberrant activation of the mTOR pathway." (PMID 40989692, 2025). "The pathogenesis of PEComas is linked to constitutive activation of the mTOR pathway." (PMID 37448552, 2023). "Both sporadic and TSC associated PEComas present mTOR pathway alterations." (PMID 33842348, 2021). "In the majority of cases examined, LAM cells and other PEComas harbour mutations in TSC-2 resulting in constitutive activation of the mechanistic (previously mammalian) target of rapamycin (mTOR), a pivotal cellular kinase controlling growth, metabolism and autophagy." (PMID 25978616, 2015). "In summary, PEComas are rare gynecological tumors, associated with activation of mTOR." (PMID 21846376, 2011). "Therefore, molecular analyses may be helpful for both the diagnostic workup of and predicting response to mTOR inhibitors in cases of malignant PEComas." (PMID 37041531, 2023). "Molecularly, PEComas often harbor TSC1/TSC2 gene alterations leading to the activation of the mTOR signaling pathway." (PMID 41479435, 2026). "Surgical resection remains the standard of care for localized disease, whereas mTOR inhibitors constitute the cornerstone of systemic therapy for advanced or unresectable PEComas." (PMID 41964900, 2026). "First-line mTOR inhibitors are an effective treatment, but metastatic PEComas eventually develop drug resistance and disease progression." (PMID 40989692, 2025).
PEComas (continued). "While cases of progression on mTOR inhibitors have been documented, this case highlights how aggressive malignant PEComas invading the mediastinum can behave and the need for more population-based studies to guide treatment paradigms in inoperable patients." (PMID 40900800, 2025). "Due to aberrant mTOR signaling, mTOR inhibitors have demonstrated efficacy in treating malignant PEComas with the phase II AMPECT trial showing median OS of 40.8 months and progression-free survival (PFS) of 10.6 months." (PMID 40900800, 2025). "mTOR inhibitors have shown efficacy in select patients with advanced or unresectable PEComas, underscoring the translational relevance of these molecular insights." (PMID 41246713, 2025). "mTOR inhibitors have shown promise in improving outcomes for patients with advanced or metastatic PEComas." (PMID 40723161, 2025). "In contrast, PEComas with TFE3 rearrangements, associated with MET pathway activation, tend to exhibit lower response rates to mTOR inhibitors." (PMID 40647483, 2025). "In this context, targeting the mTOR pathway—which is upregulated in PEComas—has shown promising results." (PMID 40647483, 2025). "TFE3-translocated PEComas are less responsive to mTOR inhibitors, and the low response rate is associated with MET pathway activation, which is one of the mechanisms of mTOR inhibitor resistance." (PMID 40989692, 2025). "In a phase II trial of patients with malignant PEComas, the effect of the intravenous administration of nab-sirolimus, an mTOR inhibitor, was examined." (PMID 40723161, 2025). "PEComas frequently contain TSC1 or TSC2 mutations, leading to aberrant activation of the mTOR pathway." (PMID 41463261, 2025). "Fyarro's clinical development focused on advanced malignant perivascular epithelioid cell tumors (PEComa), an mTOR driven rare sarcoma (~100–300 U.S." (PMID 40458962, 2025). "mTOR inhibitors have been increasingly used for the treatment of PEComas in recent years, either as a first-line treatment in inoperable malignant cases or as adjuvant therapy after surgery." (PMID 40723161, 2025). "Dysregulation of the mTOR signaling due to functional mutations or loss of TSC1 or TSC2 leads to abnormal cell growth and the development of PEComas." (PMID 39220642, 2024). "As a result, mTOR pathway contributes to tumorogenesis in PEComas, thereby giving an opportunity for target therapy with mTOR inhibitors." (PMID 38535035, 2024). "Recently, two molecular subgroups of PEComas were proposed: type 1, which responds to mTOR inhibitors, and type 2, which responds to c-MET inhibitors." (PMID 39026968, 2024). "Based on prior understanding of mTOR pathway activity in other primary malignancies, the inclusion of hormone treatment was tested in a small case series of progressive PEComas following mTOR inhibitors and revealed an intriguing effectiveness signal." (PMID 39026968, 2024). "Recently, nab-sirolimus, an albumin-bound mTOR inhibitor, was approved by the Food and Drug Administration (FDA) for PEComas, which harbor a TSC mutation, and this drug remains the only FDA-approved systemic treatment for these tumors." (PMID 36845725, 2023). "The basis for the treatment of malignant PEComas with the recently FDA-approved mTOR inhibitor, nab-sirolimus, is also reviewed." (PMID 37041531, 2023). "On the basis of this observation, mTOR inhibitors including sirolimus, everolimus, and temsirolimus, have been used in the treatment of PEComas with good clinical results as reported mostly in retrospective reviews and case reports." (PMID 37448552, 2023). "Recently, mTOR inhibitors such as sirolimus have been shown to be effective for inoperable, recurrent, or advanced PEComas." (PMID 37470853, 2023). "Together with evidence from prior studies, our results suggest that mTOR inhibitors should be the agents of choice in patients with PEComas, considering the better safety profile of these agents compared with cytotoxic chemotherapy." (PMID 37448552, 2023).
PEComas (continued). "Given these molecular characteristics, mTOR inhibitors have recently been approved by the FDA in the treatment of malignant PEComas, particularly in those with TSC1/2 alterations." (PMID 37041531, 2023). "Perivascular epithelioid cell tumors (PEComas) are associated with mutations in TSC1 and TSC2 with subsequent activation of the mTOR pathway." (PMID 35626152, 2022). "Sirolimus, a drug used to prevent transplant organ rejection, is an mTOR inhibitor also of interest as an anti-cancer drug, particularly in the treatment of perivascular epithelioid cell tumour (PEComa)." (PMID 35406393, 2022). "The majority of PEComas have a loss of function (LOF) of TSC-1 or -2 genes (commonly TSC-2 LOF), leading to increased mTOR pathway activation." (PMID 36360169, 2022). "Recently, a subdivision into two molecular subgroups of PEComas was proposed: type 1, responding to mTOR inhibitors and type 2 responding to c-MET inhibitors." (PMID 34680376, 2021). "The relatively high ORR in patients with primary uterine PEComas is consistent with that of the overall study population and contrasts with retrospective reports of lower sensitivity of uterine PEComas to mTOR inhibitors." (PMID 34637337, 2021). "A subset of malignant PEComas are associated with mutations (inactivation or deletions) of TSC1 or TSC2, negative regulators of the mTOR signaling pathway." (PMID 34637337, 2021). "Although first line mTOR inhibitors are an effective treatment, metastatic PEComas eventually progress." (PMID 33842348, 2021). "Based on the knowledge of mTOR pathway activation in other primary cancers, the addition of hormonal therapy was assessed in a small case series of progressive PEComas after mTOR inhibitors and showed an interesting efficacy signal." (PMID 34680376, 2021). "Despite being a rare tumor with no specific randomized controlled trial assessing the optimal treatment sequence, mTOR inhibitors are currently considered the most effective treatment option for metastatic PEComas." (PMID 33842348, 2021). ".Three patients with advanced uterine PEComas underwent debulking surgery followed by mTOR inhibitors: two of these obtained a complete response and the remaining patient developed progressive disease." (PMID 32685651, 2020). "The important study by Kenerson revealed that PEComas usually show increased mTOR signaling, in most cases related to impairment of TSC2 function." (PMID 31309284, 2020). "This is the basis for the use of mTOR inhibitors, sirolimus, or everolimus in the treatment of locally invasive or metastatic PEComas (IV B)." (PMID 27905051, 2016). "Despite the encouraging results of small clinical trials on the effectiveness of oral administration of mTOR inhibitors in patients with metastatic PEComas, in general, PEComas are chemotherapy- and radiotherapy-insensitive tumours." (PMID 25821471, 2015). "Since the mTOR pathway is often altered in PEComas and responses have been reported with mTOR-inhibitors such as sirolimus or temsirolimus, we decided to start a neoadjuvant treatment with sirolimus." (PMID 24575738, 2014). "Due to its rarity, data on medical treatment for PEComas originate from small case series, most of which employed the mTOR-inhibitor sirolimus." (PMID 24575738, 2014). "PEComas are usually considered chemoresistant tumors, but published reports of responses obtained with the mTOR-inhibitors sirolimus and temsirolimus provided the rationale for the use of an agent of this class." (PMID 24575738, 2014). "Other evidence to support activation of the mTOR pathway in PEComas has also recently been described." (PMID 22943457, 2012). "On the basis of published studies that showed activation of the mTOR pathway in PEComas, the institutional board approved everolimus as an off-label treatment for this patient." (PMID 22943457, 2012).
PEComas (continued). "Our data are consistent with findings published to date on the activity of mTOR inhibitors in tumors known to be biologically related to PEComas, specifically angiomyolipoma and LAM." (PMID 22943457, 2012). "Altogether, these findings support the inhibition of mTOR as a rational therapeutic target in tumors occurring in patients with TSC as well as PEComas." (PMID 22943457, 2012). "Taken together, these observations suggest that activation of mTOR through loss of the TSC1/TSC2 repressor complex, or potentially by other means, is likely a common and critically pathogenic event in PEComas." (PMID 22943457, 2012). "PEComas are associated with mutations or deletions of tuberous sclerosis associated genes TSC1 or TSC2, which act as tumor suppressor genes by regulating mTOR." (PMID 21846376, 2011). "Several studies reported partial sensitivity of malignant PEComas to mTOR inhibitors." (PMID 41479435, 2026). "Therefore, it has been proposed that PEComas can be subdivided into two molecular subgroups: type 1, which is responsive to mTOR inhibitors, and type 2, which is responsive to c-MET inhibitors." (PMID 40989692, 2025). "Unfortunately, mTOR inhibitors do not appear to improve PFS relative to standard chemotherapy regimens or provide OS benefit in TSC1/TSC2 mutated malignant PEComas." (PMID 40900800, 2025). "mTOR inhibitors have transformed the management of malignant PEComas." (PMID 40659896, 2025). "In addition, molecular alterations—particularly those involving the mTOR signaling pathway—have been increasingly identified in PEComas, offering potential avenues for targeted therapy." (PMID 40647483, 2025). "The most common genetic alteration present in sporadic or hereditary PEComas is a loss of function of the TSC1 (~ 27%) or TSC2 (~ 73%) genes, leading to the activation of mTOR signaling, which may represent a therapeutic target." (PMID 38243242, 2024). "However, some commonly used chemotherapy drugs for the treatment of advanced or metastatic PEComas include mTOR inhibitors, as dysregulation of the mammalian target of rapamycin (mTOR) pathway is a characteristic feature of PEComas." (PMID 39220642, 2024). "Malignant PEComas are rare, and we report a peculiar case of PEComa treated with mTOR inhibitors." (PMID 37692712, 2023). "There are some clinical data regarding the use of sirolimus and other mTOR inhibitors as off-label treatment for PEComas, and the PEComas showed relatively high responses to mTOR inhibitors compared to other approved antitumor drugs; however, there are few data from prospective clinical trials." (PMID 31963219, 2020). "Besides surgical resection as the treatment option of choice, clinicians should be aware of new treatment strategies using inhibitors of the mTOR signaling pathway, which is commonly activated in PEComas." (PMID 24393276, 2014). "Although the use of mTOR inhibitors in the management of TSC-associated tumors is well established, and initial studies have demonstrated their potential efficacy in PEComas, surgical intervention currently constitutes the central component of therapy for uterine PEComas." (PMID 41528496, 2026). "Abnormal activation of the mTOR pathway may be involved in the pathogenesis of PEComas through mechanisms independent of TSC gene mutations." (PMID 39220642, 2024). "In addition, because mTOR overexpression plays an important role in the development of PEcoma, mTOR inhibitors may be beneficial for PEcoma treatment." (PMID 35928867, 2022). "PEComas can be related to genetic alterations of tuberous sclerosis complex [TSC], an autosomal dominant disease due to loss of TSC1 or TSC2 genes involved in the regulation of the Phosphatidylinositol 3-Kinases [PI3K]/AKT/Mammalian Target of Rapamycin [mTOR] signaling pathway." (PMID 32685651, 2020).